NRG1 (neuregulin 1)
Diseases named in the same sentence as NRG1 in open-access papers (continued):
Sharing a sentence is not in itself a finding about the gene and the disease.
hemorrhagic stroke (3 papers, 2019 to 2024). A stroke caused by a bleed on the brain. "Using viral vectors, we expressed the Nrg1-ICD in cortical neurons and subsequently challenged them by a focal hemorrhagic stroke; our data indicated that Nrg1 intracellular signaling improved neuronal survival in the infarcted area." (PMID 31583038, 2019). "Moreover, they revealed that neuregulin-1 (NRG-1) protects cells against heme in organoids, providing a potential mechanism for modeling and studying hemorrhagic stroke." (PMID 34234646, 2021). "Therefore, NRG-1 could potentially offer a treatment to both ischemic and hemorrhagic stroke as well as extend the therapeutic window of tPA by reducing BBB permeability and hemorrhagic transformation." (PMID 38638304, 2024). "To address the role of Nrg1-ICD signaling in vivo, we employed collagenase injection as an experimental model of focal hemorrhagic stroke." (PMID 31583038, 2019).
liver cancer (3 papers, 2022 to 2025). An epithelial or non-epithelial malignant neoplasm that arises from the liver. "Hsa-miR-296-5p suppresses the epithelial-mesenchymal transition process of liver cancer via regulating NRG1 expression through cell-autonomous mechanism." (PMID 35590240, 2022).
Myocardial fibrosis (3 papers, 2011 to 2013). "NO synthase, which may be stimulated by the NRG-1/ErbB signaling pathway, is suggested to be involved in myocardial fibrosis." (PMID 24223630, 2013). "NO synthase, which can be stimulated by NRG-1/ErbB signal pathway, may also be involved in myocardial fibrosis." (PMID 21798071, 2011).
myocardial ischemia (3 papers, 2018 to 2025). A disorder of cardiac function caused by insufficient blood flow to the muscle tissue of the heart. "Available evidence indicates that neuregulin-1 (NRG-1) can provide a protection against myocardial ischemia/reperfusion (I/R) injury and is involved in various cardioprotective interventions by potential regulation of mitophagy." (PMID 39874927, 2025). "In accordance with this, a recent report demonstrated that a catheter-based intramyocardial injection of NRG1-loaded microparticles significantly improved left ventricular diastolic function in a preclinical pig model of myocardial ischemia and reperfusion." (PMID 36012430, 2022).
Nephropathy (3 papers, 2021 to 2024). A nonspecific term referring to disease or damage of the kidneys. "An endothelium-derived growth factor, NRG-1 is widely-known to be implicated in a plethora of diseases, with studies even highlighting the participation of NRG-1 in the kidney disorders." (PMID 34869303, 2021). "NRG1 has been reported to attenuate the development of nephropathy in a diabetes I mouse model." (PMID 37627594, 2023).
ovarian tumors (3 papers, 2009 to 2020). "Assessment of the levels of NRG1 and HER2 by IHC showed that levels of both HER2 and NRG1 proteins were very high compared to array of ovarian tumors tested." (PMID 30499260, 2019). "It was reported that down‐regulation of NRG1 expression could sensitize ovarian tumors to low cisplatin concentration." (PMID 32441484, 2020). "The correlation of HRG/NRG1 and ITGB3 expression might be relevant to study in ovarian tumours as well, or there might be other unknown factors that regulate the impact of ITGB3 as a biomarker." (PMID 19775429, 2009).
papillary thyroid cancer (3 papers, 2020 to 2024). "NRG1 was identified as a serum biomarker of papillary thyroid cancer." (PMID 38668354, 2024).
squamous cell carcinoma (3 papers, 2017 to 2019). A carcinoma arising from squamous epithelial cells. "Interestingly, several DM protein-coding genes, namely the LGI1, IRF2, and NRG1 genes, have been implicated in squamous cell carcinoma, which involves the same keratinocyte layer that is exclusively hijacked by HPV infection." (PMID 31892232, 2019). "Squamous cell carcinomas in general have been found to exhibit relatively high NRG1 expression compared with adenocarcinoma counterparts." (PMID 28899363, 2017).
squamous cell carcinoma of the head and neck (3 papers, 2016 to 2017). "NRG1-mediated autocrine signaling has been documented in a significant subset of head and neck tumors, and NRG1 expression is particularly enriched in squamous cell carcinoma of the head and neck (SCCHN)." (PMID 28899363, 2017). "In addition to HER2-driven cancers, preclinical data suggest that NRG1-driven cancers, which include a significant proportion of squamous cell carcinomas of the head and neck (SCCHN), are also likely to benefit from HER3-directed therapy." (PMID 27942917, 2017). "This multicenter, open-label, randomized phase II study (MEHGAN) evaluated drug efficacy in patients with recurrent/metastatic (R/M) squamous cell carcinoma of the head and neck (SCCHN) progressive on/after chemotherapy and among patients with NRG1-high tumors." (PMID 27843803, 2016).
systolic heart failure (3 papers, 2013 to 2022). Heart failure caused by abnormal myocardial contraction during systole leading to defective cardiac emptying. "The results of promising clinical trials of two different forms of recombinant NRG1 in systolic heart failure support further investigation of this biologic therapy." (PMID 36120374, 2022).
thyroid tumor (3 papers, 2017 to 2021). A benign or malignant neoplasm affecting the thyroid gland. "Also, rs2439304 is an eQTL strongly associated with the expression of NRG1 in thyroid tumor cells with p = 3.1 × 10-39 in PancanQTL." (PMID 33747362, 2021). "PROM1, NRG1, and PROM1 are related to stimulating thyroid epithelium to the progression of a thyroid tumor, and their mutation may interact to promote thyroid tumor differentiation and proliferation." (PMID 33805984, 2021).
viral infection (3 papers, 2019 to 2024). "First, we established stable BNST cells with reduced NRG1 expression through virus infection." (PMID 38331905, 2024). "Additionally, under stress conditions, including viral infection, cytotoxic agents, and oxidative stress, the activation of NRG-1/ERBB signaling has been shown to protect myocardial cells from apoptosis." (PMID 38433839, 2024).
adenoma (2 papers, 2014 to 2023). A neoplasm arising from the epithelium. "Interestingly, we observed increased mRNA expression of both Ereg and Nrg1 in intestinal tumors of Apcmin mice, which model early CRC by developing multiple adenomas throughout the length of the intestine, owing to Apc loss-mediated constitutively active Wnt signaling." (PMID 36912192, 2023).
amyloid (2 papers, 2021 to 2022). "Further understandings of NRG1 response upon amyloid pathology will allow to specify the exact synaptic events associated with CSF and plasma NRG1 modifications observed in AD patients." (PMID 35606871, 2022).
anxiety disorder (2 papers, 2021 to 2024). A category of psychiatric disorders which are characterized by anxious feelings or fear often accompanied by physical symptoms associated with anxiety. "The KLK8-mediated cleavage of neuregulin-1, synaptic adhesion molecule L1, and ephrin type-B receptor 2 has been implicated in the regulation of hippocampal neural plasticity and the pathogenesis of anxiety disorders 68-70." (PMID 33754057, 2021).
Autoimmunity (2 papers, 2013 to 2025). The occurrence of an immune reaction against the organism's own cells or tissues. "NRG1 is required for signal transduction of many sensor TIR-NLRs such as RUN1, and can cause autoimmunity when mutated, highlighting its importance in triggering HR." (PMID 40110352, 2025).
breast invasive carcinoma (2 papers, 2022 to 2024). "First, we analyzed correlation between PRCP gene expression and IGF1 (IGF1R ligand) and NRG1 (HER3 ligand) expression in 1093 cases of invasive breast cancer (TCGA database) using TIMER software." (PMID 36332175, 2022).
cerebral malaria (2 papers, 2014 to 2018). A sequestration of Plasmodium falciparum in the brain, which can cause coma and/or seizures. "For instance, it is unclear how NRG-1 activates its ErbB receptor to protect against cerebral malaria pathogenesis." (PMID 29636063, 2018). "Although NRG-1 has been studied extensively in AIS it has yet to be studied as a potential intervention against cerebral malaria." (PMID 24433482, 2014). "However, the mechanism by which NRG-1/ErbB interaction protects against cerebral malaria pathogenesis is unknown." (PMID 29636063, 2018). "Following our first report of its protective role in experimental cerebral malaria (ECM), we further examined how NRG-1 mechanistically attenuates ECM pathogenesis and reduces mortality." (PMID 29636063, 2018). "Utilizing an experimental cerebral malaria (ECM) model (Plasmodium berghei ANKA in C57BL/6), we reported that NRG-1 played a cytoprotective role in ECM and that circulating levels were inversely correlated with ECM severity." (PMID 29636063, 2018). "Our interest in signal transducer and activation of transcription 3 (STAT3) and AKT signaling pathways derives from the reported importance of STAT3 in the pathogenesis of cerebral malaria while AKT activation is a typical downstream signal molecule for NRG-1/ErbB4." (PMID 29636063, 2018). "Furthermore, we postulate that augmenting NRG-1 during ECM therapy may be an effective adjunctive therapy to reduce CNS tissue injury and potentially increase the effectiveness of current anti-malaria therapy against human cerebral malaria (HCM)." (PMID 29636063, 2018).
cervical carcinoma (2 papers, 2024 to 2025). A carcinoma arising from either the exocervical squamous epithelium or the endocervical glandular epithelium. "The NSCLC cell lines NCI-157, NCI-H322, NCI-H522, A549, NCI-H661, H1299, and the control cervical cancer cell line, C33A cells, have high levels of NRG1 mRNA." (PMID 41007372, 2025). "Relationship between mRNA expression of NRG1 in cervical carcinoma tissues and clinicopathological features of patients." (PMID 38952532, 2024). "This conclusion is further confirmed by the negative correlation (p<0.05) between the degree of DNA methylation of NRG1 gene and the expression of mRNA in cervical carcinoma shown in this study." (PMID 38952532, 2024). "Correlation analysis between mRNA expression and promoter methylation of NRG1 in cervical carcinoma tissues." (PMID 38952532, 2024). "If the DNA methylation status of NRG1 gene is identified as an epigenetic marker from an epigenetic point of view, molecular therapies for patients with cervical carcinoma can be used as a reference for the targeted therapy of cervical carcinoma." (PMID 38952532, 2024). "The MSP method was used to detect the methylation status of NRG1 in cervical carcinoma group, precancerous lesion group and control tissue group, and to analyze the relationship between the methylation status of NRG1 and its expression." (PMID 38952532, 2024). "This present study not only confirmed that NRG1 could be expressed in cervical carcinoma tissues, HSIL tissues and normal cervical tissues, but also showed its relatively low expression in cancerous tissues along with the aggravation of cervical site lesions." (PMID 38952532, 2024). "DNA methylation of NRG1 gene may be involved in the occurrence and development of cervical carcinoma." (PMID 38952532, 2024). "Comparison of mRNA expression rates of NRG1 in different cervical carcinoma tissues." (PMID 38952532, 2024). "In this study, the positive protein expression of NRG1 gene was firstly detected by immunohistochemical assay, and the results showed a lower protein positive expression rate of NRG1 gene in cervical carcinoma tissues than in both precancerous lesion and control groups." (PMID 38952532, 2024). "All of these suggest a role for NRG1 in the development of cervical carcinoma." (PMID 38952532, 2024). "Abnormal DNA hypermethylation of NRG1 gene inhibits the expression of mRNA and protein in the progression of cervical tissue from normal to cancerous state, which is involved in the occurrence and development of cervical carcinoma." (PMID 38952532, 2024). "Thus, it can be concluded that the hypermethylation of NRG1 gene may have a close bearing on the occurrence and development of cervical carcinoma." (PMID 38952532, 2024). "Moreover, the methylation rate increased sequentially with the aggravation of the lesion site, suggesting a possible correlation between the abnormal expression of NRG1 in cervical carcinoma tissues and the methylation status of this gene, as shown in Table-VII." (PMID 38952532, 2024). "Accordingly, he speculated that NRG1 is likewise a negative regulatory factor for the growth of cervical carcinoma cells, and the reduction or absence of its expression is a favorable condition for the development and deterioration of cervical carcinoma." (PMID 38952532, 2024). "It was also found by immunohistochemical studies combined with clinical statistics that the mRNA expression of NRG1 gene in cervical carcinoma tissues was independent of the patients’ age, but significantly correlated with lymphatic metastasis, tumor clinical staging, and surgical pathology staging." (PMID 38952532, 2024).
colorectal adenoma (2 papers, 2019 to 2023). An adenoma that arises from the colon or rectum. "Indeed, hypermethylation of the NRG1 promoter was previously shown to occur in colorectal adenomas and cancer, suggesting tumor suppressive function of NRG1 in CRC." (PMID 36912192, 2023).
colorectal tumor (2 papers, 2019 to 2025). "In vitro, colorectal tumor stem cells with increased HER3 expression exhibited resistance to vemurafenib in the presence of the HER3 ligand, NRG-1." (PMID 31672130, 2019).
demyelination (2 papers, 2018 to 2021). "The Karimi-Abdolrezaee group showed that Neuregulin-1 promotes remyelination in lysolecithin-induced demyelination and they found a corresponding increase of Treg in lesions of Neuregulin-1 treated animals 14 days post-lesioning." (PMID 29720228, 2018). "Together, SZASD showed a therapeutic effect on demyelinated mice, and the improvement of demyelination might not be through the NRG-1 pathway." (PMID 33708250, 2021).
disseminated candidiasis (2 papers, 2022 to 2024). Systemic candidiasis occurs when Candida yeast enters the bloodstream and may spread (becoming disseminated candidiasis) to other organs, including the central nervous system, kidneys, liver, bones, muscles, joints, spleen, or eyes. "To do so, we deleted NRG1 in four poorly filamenting clinical isolates and examined the effect of those mutations on in vitro and in vivo filamentations and gene expression, as well as on virulence in the mouse disseminated candidiasis model." (PMID 38376205, 2024). "Here, we describe our investigation of the effect of strain background on the role of the transcriptional repressor Nrg1 during in vitro filamentation, in vivo filamentation, and disseminated candidiasis in a mouse model." (PMID 38376205, 2024). "Forced constitutive expression of NRG1 in SC5314 established the need of morphotype switching for pathogenicity of C. albicans during disseminated candidiasis, while enforced filamentation due to constitutive deletion of NRG1 lowered intestinal colonization of C. albicans." (PMID 35404986, 2022).
Down syndrome (2 papers, 2017 to 2021). "This does not come as a total surprise, as several known HSCR genes (e.g., KBP, SOX10, NRG1, IKBKAP, ZEB2, PHOX2B) are involved in both CNS and ENS pathologies and the fact that HSCR is strongly associated with Down syndrome." (PMID 28274275, 2017). "Associated common risk haplotypes have epistatic interactions, not only with each other, but also with known HSCR genes -such as RET and NRG1 - and modify HSCR penetrance in monogenetic syndromes and Down syndrome." (PMID 34358225, 2021).
endometrial cancer (2 papers, 2008 to 2024). Primary or metastatic malignant neoplasm involving the endometrium (mucous membrane that lines the endometrial cavity). "Our preclinical findings, however, do suggest that increased expression of EGFR ligands such as amphiregulin, TGF-α, epiregulin, or NRG1 may also be associated with sensitivity to lapatinib in endometrial cancer." (PMID 18334972, 2008).
endothelial dysfunction (2 papers, 2018 to 2021). In vascular diseases, endothelial dysfunction is a systemic pathological state of the endothelium (the inner lining of blood vessels) and can be broadly defined as an imbalance between vasodilating and vasoconstricting substances produced by (or acting on) the endothelium. "Since Nrg1 protects against endothelial dysfunction by enhancing eNOS function and ErbB2 is a receptor for Nrg1, we speculated Nrg1-ErbB2 interaction in the coronary artery endothelial cells." (PMID 34039018, 2021). "Since NO generated by eNOS is critically important for the protection against endothelial dysfunction of coronary artery in I/R, we determined the mechanism by which Nrg1 might induce NO production." (PMID 34039018, 2021). "Consistent with this notion, when Nrg1 neutralizing antibody was injected into mice before RIPC of FA, the protective effect of RIPC in endothelial dysfunction of the coronary arteries was abrogated concomitant with loss of a protective effect against MI." (PMID 34039018, 2021). "In addition to protection against endothelial dysfunction, RIPC of FA protected against MI, the specific role of remotely released Nrg1β is established in MI, as neutralizing antibody to Nrg1 abrogated the protective effect of RIPC." (PMID 34039018, 2021).
hemangioma (2 papers, 2021 to 2022). A benign vascular lesion characterized by the formation of capillary-sized or cavernous vascular channels. "CASC9 has been reported to act as a ceRNA to target the tumor suppressor miR-125a-3p and regulate neuregulin-1 (NRG1) to promote hemangioma endothelial cell invasion and migration." (PMID 34711117, 2021).
Hepatic steatosis (2 papers, 2022). Steatosis is a term used to denote lipid accumulation within hepatocytes. "The other promising genes and proteins that may play important roles in mediating the reduction of liver steatosis by soy protein include hepatic Neuregulin 1 (NRG1), Erb-B2 Receptor Tyrosine Kinase 3 (ERBB3) and mitogen-activated protein kinase interacting serine/threonine kinase 1 (MKNK1)." (PMID 35678936, 2022). "ERBB3 could be modulated through phosphorylation by NRG1 to alleviate liver steatosis." (PMID 35678936, 2022). "Moreover, recently NRG1 has been demonstrated via the same mechanism of ErbB3-AKT activation, decreased TG levels, and inhibited steatosis in a hepatic cellular model of nonalcoholic fatty liver disease, thus validating a protective role of NRG1 in the pathogenesis of hepatic steatosis." (PMID 35625715, 2022).
inflammatory bowel disease (2 papers, 2024 to 2025). A spectrum of small and large bowel inflammatory diseases of unknown etiology. "In inflammatory bowel disease, upregulation of the NRG1/ERBB3 axis activates PI3K/Akt signaling, sustaining intestinal epithelial proliferation and damage repair." (PMID 41178971, 2025). "Patients with inflammatory bowel disease also exhibited an increase in NRG1+IL1R1+ fibroblasts and an interaction of NRG1–ERBB between IL1R1+ fibroblasts and colonic epithelial cells." (PMID 38674054, 2024).
intestinal tumors (2 papers, 2023 to 2025). "S. flexneri C.11 and its metabolites enhanced the binding of ERBB3 to Nrg1, activating the PI3K-AKT and mTOR pathways, which subsequently promoted the malignant transformation of normal intestinal epithelial cells and progression of intestinal tumors in mice." (PMID 40911847, 2025).
leukemia (2 papers, 2013 to 2021). A malignant (clonal) hematologic disorder, involving hematopoietic stem cells and characterized by the presence of primitive or atypical myeloid or lymphoid cells in the bone marrow and the blood. "Quantitative promoter PCR was performed in selected, potential ERG targets genes related to PI3K or leukemia including AR, NUMB, NRG1, and ETS1 in AML A-E, and T-ALL ChIPs." (PMID 23300998, 2013).